VHL (von Hippel-Lindau tumor suppressor)
Diseases named in the same sentence as VHL in open-access papers (continued):
Sharing a sentence is not in itself a finding about the gene and the disease.
tumor (continued). "In pre-clinical models of ccRCC, HIF suppression is necessary and sufficient for VHL-dependent suppression of tumor growth." (PMID 21949687, 2011). "The prevalence of VHL inactivation in ccRCC tumor DNA from this large well-characterized case-series of sporadic RCC is one of the highest reported in the literature, and is consistent with recent publications including our previous report." (PMID 22022277, 2011). "The RCC tumor xenograft was established by inoculation with OS-RC-2 cells in nude mice to verify VHL gene therapy effects." (PMID 21513541, 2011). "This region contains the Von Hippel-Lindau (VHL) gene, a tumour suppressor thought primarily responsible in the pathogenesis of hereditary and sporadic clear cell RCC." (PMID 22738081, 2011). "In order to validate the potential transport potent of the three novel modified PEI in vivo, we used VHL gene, a tumor suppressor gene that is usually inactivation or absence in RCC, to treat the RCC model on nude mice." (PMID 21513541, 2011). "Combination of epigenetic and genetic silencing characterizes several tumor-suppressor and cancer-predisposing genes such as P16, MLH1, VHL and others." (PMID 21853109, 2011). "The mean tumor volume in FA-PEAs:VHL-treated mice was decreased about 30% compared to the control group." (PMID 21513541, 2011). "In summary, this comprehensive analysis of 470 well-characterized ccRCC patient tumor DNA samples observed VHL inactivation through genetic or epigenetic mechanisms in 86.6% of cases." (PMID 22022277, 2011). "The von Hippel-Lindau tumor suppressor -hypoxia-inducible factor (VHL-HIF) pathways are key players in tumor hypoxia survival." (PMID 21689475, 2011). "von Hippel-Lindau disease arises from heterozygous germline mutations in the VHL tumour suppressor gene, which resides on chromosome 3p25, and it is characterised by clear cell RCC, hemangiomas, pheochromocytomas, and other tumour types." (PMID 21673679, 2011). "The expression status of a target gene Von Hippel-Lindau (VHL) in treated tumor tissues was analyzed by semiquantitative RT-PCR and immunohistochemistry." (PMID 21513541, 2011). "Cancer-relevant genes on 5q include the LOX gene, which has been shown to play an essential role in hypoxia-induced metastasis, the later is triggered by the disrupted VHL gene in the tumor cells." (PMID 20671976, 2010). "Concordantly, loss of PIASy suppresses the cell migration of VHL positive cells, indicating that SUMO modification abolished the inhibitory effect of VHL on tumor cell migration." (PMID 20300531, 2010). "Clear-cell renal cell carcinoma (ccRCC), the most frequent subtype of renal cancer, is characterized by inactivation of the von Hippel-Lindau (VHL) tumour suppressor gene in about 70% of the tumours." (PMID 20492653, 2010). "Genes promoting cancer progression (u-PAR, VEGFC, and HIF1α) and tumour suppression (VHL, RASSF1, and FHIT) of NSCLC were significantly (P<0.05) down- or upregulated after Enz treatment in H460, A549, and H1299 cells, respectively." (PMID 20736951, 2010). "Mutated VHL prevents appropriate normoxic degradation of HIF-1α and, as such, CAIX is highly expressed in mutated VHL-related tumours, independently of the extent of tumour necrosis." (PMID 20461082, 2010). "ccRCC is a unique setting in which to study these microRNAs, given that VHL loss constitutively stabilizes one or more HIF factors, thereby creating a pseudo-hypoxic scenario in ccRCC tumor cells." (PMID 20420713, 2010). "Nevertheless, inactivation of VHL by itself cannot explain the broader variety of tumour types that have elevated HIF protein." (PMID 20461086, 2010). "Tumour-suppressor genes VHL, RASSF1, and FHIT are downregulated in NSCLC, which are implicated in the ubiquitin ligase system, cell-cycle regulation, and apoptosis, respectively." (PMID 20736951, 2010). "Tumours with VHL alterations and high VEGF levels (Group 2) probably reflect additional molecular events following initial VHL alteration." (PMID 19755989, 2009).
tumor (continued). "Hypoxic tumour cells were reoxygenated 6 h postirradiation, leading to von Hippel-Lindau (VHL)-dependent proteolysis of HIF-1α and a resultant decrease in HIF-1 activity." (PMID 19223896, 2009). "Classical tumour suppressor genes and genes involved in chemosensitivity, such as hMLH1, p16, p15, Rb, VHL, E-cadherin, GSTP1, and BRCA1, or the DNA repair gene MGMT, undergo epigenetic inactivation by hypermethylation of their regulatory regions." (PMID 19144202, 2009). "The VHL tumour suppressor gene is inactivated in about 75% of clear-cell renal cell carcinoma (CC-RCC) patients." (PMID 19319136, 2009). "Reintroduction of either VHL product into VHL null cells inhibits in vivo tumor formation, signifying that both contain tumor suppressor functions." (PMID 19602254, 2009). "Vascular endothelial growth factor levels were measured in the culture supernatant from RCC-10 and VHL+53 tumour cell lines under normal and hypoxic (1% O2) conditions." (PMID 19277038, 2009). "In RCC aberrant DNA methylation of the tumor suppressor gene VHL is found at a high frequency, whereas the frequencies of DNA promoter methylation of other tumor suppressor genes vary in this malignancy." (PMID 19857250, 2009). "Inactivation of the von-Hippel-Lindau (VHL)- tumor suppressor gene is a well-studied example of a pseudo-hypoxia reaction increasing glycolytic flux via HIF-1 in tumor cells." (PMID 19949549, 2009). "There is increasing evidence that ubiquitination of HIF-α is necessary for VHL-dependent suppression of tumor progression." (PMID 19602254, 2009). "By quantitative RT-PCR and immunoblot, we report that the SHH signaling pathway is constitutively reactivated in tumors independently of the von Hippel-Lindau (VHL) tumor suppressor gene expression which is inactivated in the majority of CRCC." (PMID 20015350, 2009). "The potential for such a strategy is demonstrated by the results of Euclidean cluster analysis that grouped most tumours into groups consistent with their histopathology/VHL status." (PMID 19493342, 2009). "In most series, tumours with biallelic inactivation of the VHL gene are compared with tumours presenting at least one functional allele." (PMID 19755989, 2009). "Clear cell carcinomas, which account for 75% of all RCC subtypes, appear to contain an inactivated von Hippel–Lindau (VHL) tumour suppressor gene in at least 60% of these tumours." (PMID 18594533, 2008). "The clinical phenotype results from molecular abnormalities of the VHL tumor suppressor gene, mapped to human chromosome 3p25-26." (PMID 18416845, 2008). "Studies to date have shown that downregulation of HIF-α is necessary for VHL dependent tumor suppression in some model systems." (PMID 17598890, 2007). "It is a tumour suppressor gene and a tumour cell develops when inactivation of both copies of the VHL gene occurs." (PMID 17922902, 2007). "Inactivation of the VHL tumour suppressor gene is thought to result both in development of tumors in the von Hippel-Lindau (VHL) disease (MIM #19330) and in sporadic clear-cell RCC." (PMID 17997830, 2007). "Here 26 tumours (21 fixed and 5 frozen tumours, ie 54%) were successfully analyzed regarding the VHL gene." (PMID 17997830, 2007). "In fact, expression of such a VHL mutant, which retains the ability to negatively regulate HIF-2α, suppresses tumor formation of VHL null RCC cells in vivo." (PMID 17140440, 2006). "Successful RCC tumor suppression by VHL requires the negative regulation of hypoxia inducible factor alpha (HIF alpha) protein and its downstream targets." (PMID 17140440, 2006). "Defining the HIF-2 targets responsible for VHL null RCC tumor progression is important to understand the mechanisms of renal tumor development." (PMID 17140440, 2006).
tumor (continued). "Together, these data imply that MT1-MMP is the HIF-2α target gene responsible for the increased tumor cell invasion observed in VHL mutant RCC cells." (PMID 17140440, 2006). "Our results suggest that MT1-MMP is a major mediator of tumor cell invasiveness and type I collagen degradation by VHL RCC cells that express either MT1-MMP or HIF-2alpha." (PMID 17140440, 2006). "Recently, the expression of CXCR4 on RCC and NSCLC tumor cells was shown to be regulated by hypoxia and the VHL/HIF-1α pathway." (PMID 17083723, 2006). "Again, different VHL genotypes, identical to the earlier genotypes, were observed, showing that tumor heterogeneity appears to play a role." (PMID 15932632, 2005). "A transcription profile of reduced oxidoreductase is detected in all three of these tumor types, together with an angiogenesis/hypoxia profile typical of VHL dysfunction." (PMID 16103922, 2005). "For 10 RCC cases, we observed different VHL genotypes in different tumor samples obtained from one tumor." (PMID 15932632, 2005). "A diffuse cytoplasmic CA9 pattern of expression as a specific feature of VHL cases was observed in our series, differing from the strong membranous staining that we found in undifferentiated tumours." (PMID 15558070, 2005). "The von Hippel-Lindau (VHL) tumor suppressor functions as a ubiquitin ligase that mediates proteolytic inactivation of hydroxylated α subunits of hypoxia-inducible factor (HIF)." (PMID 15361934, 2004). "The tumor suppressor function of VHL was further substantiated by the finding that reintroduction in a cell line blocked its ability to form tumours." (PMID 14647151, 2003). "Their polarization is shaped by ELR+ CXC chemokines (CXCL1, CXCL8), cytokine signals, systemic inflammation, hypoxia driven by VHL/HIF pathways, and tumor-intrinsic oncogenic alterations such as PTEN loss, ERβ- and c-Myc-dependent programs, as well as epigenetic remodeling." (PMID 41705247, 2026). "The median target tumor volume was smaller in VHL cases (3.49 cc vs. 6.5 cc, p = 0.038)." (PMID 41996317, 2026). "Importantly, pharmacologically inhibiting PEA15 using PEA15 ASO drugs attenuated tumor burden and restored VHL function in a xenograft mouse model." (PMID 41958708, 2026). "Furthermore, the inclusion of a diverse cohort with various advanced manifestations of VHL broadens the applicability of the findings across different tumor types." (PMID 41174705, 2025). "Of the 61 individuals who did not meet the clinical VHL criteria, 16 patients (26%) had a VHL-mutated tumor." (PMID 40393028, 2025). "The misfolding of VHL protein may be particularly relevant in GBM as this tumor often exhibits hypoxia-driven progression, and a defective VHL-HIF axis could lead to angiogenesis, metabolic dysregulation, and therapeutic resistance." (PMID 41002413, 2025). "A tumor landscape analysis was conducted on the remaining 2539 patients who were positive for the somatic VHL variant(s), had comprehensive tumor data, and a subset of whom had been evaluated in genetics but did not have the germline VHL variants (Cohort 2)." (PMID 40647474, 2025). "A vast majority of the patients would be willing to take a pill (strongly agree or agree) that could slow the growth of their VHL-related tumor and delay the time until surgery." (PMID 40796357, 2025). "Among the patients with P/LP variants, only 65.5% (19/29) had ≥2 VHL component tumors, 10% (3/29) had only one component tumor, and another 14% (4/29) had only non-VHL tumors." (PMID 40647474, 2025). "However, under VHL knockout conditions, the anti-tumor efficacy of Curcumol was markedly attenuated, as reflected by increased tumor burden, enhanced glycolytic activity, and re-emergence of EMT phenotypes." (PMID 41008845, 2025). "Subtype C1 exhibits a high frequency of mutations in genes associated with the pseudohypoxia pathway, such as VHL and SDHB, suggesting a unique adaptation to hypoxic conditions that may drive tumor progression." (PMID 41400463, 2025).
tumor (continued). "This suggests that mutation in VHL leads to the initial activation of EPO expression in renal tumors, subsequently enhancing HIF1A activity, and sustained hypoxia is essential for maintaining EPO expression in the tumor microenvironment." (PMID 40332447, 2025). "At 72 months, the PFS was 91.1% for CR and 55.8% for non-CR, indicating CR superior regarding long-term local tumor control in VHL-associated cases, with significantly worse outcomes observed in those with non-CR." (PMID 39950840, 2025). "Importantly, restoring functional VHL in cells significantly reduced tumor growth compared to the mutant VHL cells." (PMID 41226668, 2025). "This included MVD and GLUT1 expression in tumors with mutated VHL, mTOR phosphorylation in tumors with activating mutations in PI3K/AKT/mTOR pathway genes, H3K36me3 status and mutations in SETD2 and, lastly, the tumor cell proliferation rate and presence of multiple driver gene mutations." (PMID 40352587, 2025). "Furthermore, NK cells in VHL-restored tumors showed an activated phenotype with the ability to reduce tumor spheroid size." (PMID 40736709, 2025). "Clinical translational level: the current model relies mainly on traditional clinical metrics (such as tumor size and staging) but does not incorporate some of the most recent detection metrics (such as PD-L1 protein level and VHL mutation status)." (PMID 40800127, 2025). "The JX-594-induced decrease in tumor volume was the most significant in tumors associated with BAP1 mutations as opposed to tumors with VHL, PBRM1, and SETD2 mutations (P < 0.01)." (PMID 40856833, 2025). "Recent studies reveal VHL exhibits significant antitumour effects on various tumor cells." (PMID 41030787, 2025). "CA9 is constitutively overexpressed in ccRCC due to VHL gene loss, with 88.2% of tumours showing CA9 upregulation independent of VHL mutation status." (PMID 41375084, 2025). "We identified truncal VHL loss in all the patients, and although this is a major driver of the difference in metabolism between tumour and normal tissue, it is unlikely to contribute to the intratumoral metabolic heterogeneity detected using HP 13C-MRI." (PMID 40002163, 2025). "Together, these results reveal several changes in the secretome between VHL-mutated and -restored RCC tumors, and that CXCR2 ligands may influence infiltration the NK cell infiltration into VHL-restored tumor spheroids." (PMID 40736709, 2025). "Importantly, we present a novel VHL-related pathway which can be therapeutically targeted to inhibit ccRCC tumor development." (PMID 40240354, 2025). "Notably in VHL-deficient RCC, there is a pronounced preference for HIF-2α expression, which correlates with enhanced tumor growth, while HIF-1α appears to inhibit tumor proliferation." (PMID 39470609, 2025). "Additionally, recent studies demonstrated that activation of the VHL/HIF-1α/VEGF pathway relates with tumor cell occurrence, growth, prognosis, and drug resistance." (PMID 41030787, 2025). "Tumor mutation burden (TMB) analysis revealed that the high-risk group exhibited significantly higher mutation frequencies compared to the low-risk group, particularly in key driver genes such as VHL and PBRM1." (PMID 40909272, 2025). "Moreover, polyethyleneimine-derived nanoparticles with VHL plasmids successfully reduced tumor volume in BALB/c nude mice with established renal cell carcinoma." (PMID 41226668, 2025). "Based on our datasets, we found that FABP5 mRNA expression showed a significant difference between the adjacent and tumor tissues with VHL mutation, but not in the VHL wild‐type samples." (PMID 40391655, 2025). "In an asymptomatic VHL-associated tumor where there is no immediate threat to survival, a balance between efficacy and acceptable toxicity becomes the key factor that influences the choice of targeted therapy." (PMID 41458689, 2025).
tumor (continued). "Although we observed increased ICAM-1 expression in VHL-mutated tumor spheroids, neutralization of ICAM-1 did not impact on the infiltration of NK cells." (PMID 40736709, 2025). "Given that several changes related to tumor progression and immunomodulatory pathways in ccRCC upon VHL restoration were observed, secretome analysis of pVHL and 786-O spheroids was performed to investigate additional underlying mechanisms of increased NK cell infiltration in VHL-restored tumors." (PMID 40736709, 2025). "This could be explained by the presence of a mutation in the BRK1 gene which has been previously shown to confer protection to VHL patients from developing this type of tumor." (PMID 41302074, 2025). "The VEF requires at least one VHL-related tumor or feature in the personal history." (PMID 40647474, 2025). "However, a critical gap remains in understanding how restoration of VHL impacts heterogeneous tumor subpopulations." (PMID 41226668, 2025). "Furthermore, our analyses identified several factors that influence radiological and clinical outcomes, including patient demographics, VHL status, and tumor characteristics." (PMID 40091097, 2025). "The VHL protein acts as a tumor suppressor by regulating cellular responses to hypoxia." (PMID 40937003, 2025). "Their analyses, which examined variables including VHL status, sex, and radiosurgical method, indicated that none of these parameters exhibited significant associations with tumor progression." (PMID 40091097, 2025). "Clear cell RCC (ccRCC), the predominant histological subtype, is characterized by the inactivation of the von Hippel-Lindau (VHL) tumor suppressor gene and subsequent activation of hypoxia-inducible factors (HIFs), which drive angiogenesis and tumor progression." (PMID 41029457, 2025). "A frameshift alteration detected in the BCR gene in MC-LMP and no VHL gene mutation compared to ccRCC suggests likely separate clonal evolutionary mechanisms, despite the two neoplasms sharing overlapping histomorphology." (PMID 40860802, 2025). "Furthermore, while genomic intra- and inter-tumour heterogeneity has been extensively documented in sporadic ccRCC, it remains poorly characterised in VHL-ccRCC." (PMID 41241877, 2025). "However, although the individuals are closely related, they each present with different tumor sites highlighting intra-familial variability of VHL manifestations." (PMID 41302074, 2025). "As such, a rational approach to validate the TICs of ccRCC may be to inactivate VHL specifically in one of these RSPCs, and examine the tumor-initiating property of the resultant mutant progenitor cells." (PMID 39920694, 2025). "Using RCC tumor models with WT VHL, we demonstrate that ANGPTL4 behaves as a tumor suppressor." (PMID 39105498, 2024). "Tumor-derived exosomes can stimulate angiogenesis by delivering pro-angiogenic factors to endothelial cells, the building blocks of blood vessels, with exosomal miRNA-155 promoting angiogenesis by targeting VHL, a negative regulator, leading to increased vascularization and tumor growth." (PMID 40027309, 2024). "Interestingly, all of our patients with VHL had synchronous bilateral tumours already in paediatric age." (PMID 39673085, 2024). "However, chromosome 3 is home to multiple tumor suppressors important in many cancers (VHL, SETD2, PBRM1) in addition to BAP1, making it unclear in which cancers BAP1 loss is biologically important." (PMID 39554490, 2024). "In ccRCC, TAMs may support tumor fitness or disease progression, at least in part, by the proinflammatory action of CX3CL1 driven by VHL loss." (PMID 38618956, 2024). "In addition, intratumor heterogeneity (ITH), tumor VHL status, CTLA4 methylation levels, age, chromosomal changes, etc., are also important factors for predicting PD1/PD-L1 efficacy." (PMID 39014460, 2024). "Furthermore, we established primary tumor cells with considerable ciliation from two VHL-wt ccRCC patients." (PMID 39389955, 2024).